EGFR (epidermal growth factor receptor)
Diseases named in the same sentence as EGFR in open-access papers (continued):
Sharing a sentence is not in itself a finding about the gene and the disease.
tumor (continued). "In NIFTP (low-risk tumor) EGFR is overexpressed and follows the canonical pathway of signaling through ERK pathway, internalization and recycling to plasma membrane and ending with degradation." (PMID 37114127, 2023). "Over-expression of EGFR and its enhanced signaling are associated with uncontrollable proliferation, tumor angiogenesis, cellular invasion and metastasis, and resistance to some therapy methods." (PMID 36838773, 2023). "In tumor xenograft models, the addition of DS-1205c restored sensitivity to EGFR TKIs in cells with the EGFR exon 19 deletion mutation (T790M-negative)." (PMID 36892745, 2023). "Levels of CD8+ T cells were found to be higher in the EGFR wild-type and rare variants groups than in the L858R and exon 19 deletion groups in both tumor and peritumoral regions (all p < 0.001)." (PMID 37033978, 2023). "Prior to this work, the same research group associated the existence of a HER2+/EGFR+/HPSE+/Notch1+ population in tumor lines generated from patient CTCs with the generation of BM." (PMID 38022574, 2023). "In a previous study, we determined that the 1-year tumor control rate after SRS was higher in the EGFR mutation group (90.5%) than in the EGFR wild-type group (79.4%), and EGFR mutation status was correlated with overall survival." (PMID 36676186, 2023). "In vitro and in vivo studies have demonstrated that EGFR overexpression is associated with greater resistance to radiation therapy and lower sensitivity to cisplatin in several tumour types." (PMID 38414930, 2023). "In conclusion, our results demonstrated that the detection rate of the EGFR T790M mutation using plasma samples was related to the tumor burden, especially the number of metastatic organs." (PMID 36900237, 2023). "To investigate the clinical significance of the HSP70 family genes in LUADs, we analyzed a human LUAD dataset, containing crucial patient information such as tumor EGFR mutation status, gene expression profile, patient TKI-treatment history, and OS." (PMID 37178919, 2023). "Consecutive mutations within EGFR further regulates rich Akt signaling associated with enhanced tumor development." (PMID 38170015, 2023). "The results of this study also show that EGFR-TKI targeted combined chemotherapy is associated with improved levels of tumor markers and improved treatment effect." (PMID 37250563, 2023). "At the multivariate analysis, in the L-sided tumor group, third line regimen (anti-EGFR vs R/T) was independently associated with PFS [HR 0.45 (95% CI 0.25–0.80), p=0.006], but not with OS." (PMID 36895480, 2023). "In detail, EGFR positivity or ALK-1 rearrangements (which are mutually exclusive in their occurrence) are associated with the worsening of tumor progression." (PMID 37240478, 2023). "Whilst a handful of protein targets have been explored for CAR T cell therapy for GBM,9, 10, 11 a truncation mutation of the epidermal growth factor receptor (EGFR), EGFRvIII, has been of great clinical focus because of its tumor‐restricted expression." (PMID 36890859, 2023). "As expected, the EGFR amplification associated with higher expression of EGFR mRNA in both primary and recurrent tumours (p = 0.00013 and p = 0.0017, respectively, Wilcoxon rank-sum test)." (PMID 36765632, 2023). "A number of clinical studies in NSCLC have shown that the degree of infiltration of tumor-associated macrophages positively correlated with disease progression and resistance to EGFR-TKIs37,38." (PMID 38110561, 2023). "The epidermal growth factor receptor (EGFR) is a transmembrane protein that, when mutated, can promote rapid cell proliferation and tumor progression in NSCLC." (PMID 37958300, 2023). "Previous studies have reported that gene polymorphisms, simultaneous genomic mutations, or tumor size can affect the efficacy of EGFR-TKIs." (PMID 36835972, 2023). "Multiple studies and meta-analyses evaluated liquid biopsy utility when the tumor tissue is missing, particularly for EGFR mutations detection." (PMID 37445976, 2023).
tumor (continued). "Intriguingly, systematic analysis of mutated tumor genes identified EGFR, MET, BRAF, and TERT as determinants in LUAD, and NOTCH, FGFR1, SOX2, and PI3CA as determinants in LUSC." (PMID 37046851, 2023). "Here, we showed that the cisplatin resistance of tumor cells is closely linked to secretory autophagy-mediated EGFR hyperactivation via the transcriptional induction of TRPV1 by NANOG." (PMID 37165076, 2023). "Due to their function of regulating the expression of relevant proteins that are involved in the EGFR signaling pathway, they cause tumor cell apoptosis, proliferation, migration, and invasion." (PMID 37446288, 2023). "EGFR overexpression on immunohistochemistry (IHC) is associated with tumor progression and poor survival in many cancers." (PMID 36900187, 2023). "Around 50% of the cases were stained PD-L2+ on tumor cells, with 30% resulting in PD-L2high (> 50% positive cells) and is associated with an EGFR mutation and a lower stage of the tumor." (PMID 36931099, 2023). "The gold standard for EGFR T790M testing is tissue biopsy, but this is limited by risk, feasibility, insufficient tissue sample, patient preference and the presence of tumour heterogeneity in the occurrence of resistance mechanisms." (PMID 37894366, 2023). "Numerous human cancers expressed EGFR, which has been linked to tumor progression and grade, as well as a poor cancer prognosis." (PMID 38008767, 2023). "It is hoped that the expansion and anti-tumor function of these EGFR mutation-derived neoantigen-specific T cells can be augmented and reinvigorated by ICI therapy, therefore enhancing treatment efficacy." (PMID 37766136, 2023). "We next aimed to elucidate the underlying mechanism implicated in secretory autophagy-mediated EGFR activation in cisplatin-resistant tumor cells." (PMID 37165076, 2023). "Mutations in EGFR lead to its constitutive activation, protein over-expression, and tumour progression." (PMID 38116291, 2023). "Several studies have shown that EGFR‐TKI can cause some changes in the tumor immune microenvironment (TME) during the treatment of NSCLC." (PMID 37584242, 2023). "In other tumours, EGFR and HER2 co-expression has been associated with an increase in tumour aggressiveness and a worse prognosis, in comparison with either receptor expression." (PMID 38414930, 2023). "The results of our study show that the best method for predicting the disease prognosis is the mutational characterization of the EGFR signaling pathway genes in the patient’s plasma (vs. tumor tissue)." (PMID 37176143, 2023). "Tumor-associated macrophages have been found to regulate epidermal growth factor receptor (EGFR)/β-Catenin signaling pathway to promote cell proliferation, invasion and sorafenib-resistance." (PMID 37181755, 2023). "Fortunately, another fourth-generation TKI, CH7233163, exhibited even more potent anti-tumor activity against the EGFR ex19del-T790M-C797S triple mutation." (PMID 37041601, 2023). "Rare EGFR mutations, including at positions L718, L792, G724, and G796, were also reported as mechanisms leading to tumor cells’ resistance to osimertinib." (PMID 36765799, 2023). "We next attempted to elucidate the underlying mechanism responsible for EGFR hyperactivation in cisplatin-resistant tumor cells." (PMID 37165076, 2023). "Compared with the corresponding tumor tissues, the analytical sensitivity for the detection of EGFR mutations in plasma samples by both cfDNA assays was 69.2% (with a 95% confidence interval (CI, 38.6–90.9%))." (PMID 37372399, 2023). "These drugs have shown significant clinical benefits in terms of tumor response rate, progression‐free survival, and overall survival in patients with EGFR‐mutated NSCLC." (PMID 37901797, 2023). "NE tumor populations predicted to display increased cellular proliferation by mean diffusivity (MD) MRI metrics are uniquely associated with EGFR amplification and CDKN2A homozygous deletion." (PMID 37770427, 2023).
tumor (continued). "BC expression in the EGFR‐mutated tumours was also significantly higher than that in the non‐EGFR‐mutated LUAD tumours, suggesting BC level association with the EGFR‐mutated proliferation signals." (PMID 36650118, 2023). "Both cfDNA assays revealed that nine of the sixteen corresponding samples carried consistent EGFR mutations in the plasma and the corresponding tumor tissues." (PMID 37372399, 2023). "In recent years, some studies used blood samples instead of biopsies to assess EGFR mutation status by analyzing circulating tumor DNA (ctDNA)." (PMID 37014500, 2023). "Mutations detected in ccfDNA at progression only and associated with treatment resistance were identified in four patients with an activating EGFR mutation in the pretreatment tumor biopsy and treated with first-line EGFR-TKI." (PMID 37686200, 2023). "The increased local temperature associated with significant tumor cell death was observed, and the authors suggested targeting EGFR combined with GNR as a suitable approach for PTT." (PMID 37046740, 2023). "YAP1_high tumor with EGFR mutation had a lower activated immune cell infiltration such as NK cells, CD8+ T cells, and helper T cells than YAP1_low tumor." (PMID 37388902, 2023). "The abundance of EGFR mutations differs among tumors, or in different samples obtained from the same tumor, because mutant and wild-type (WT) EGFR can exist concurrently in the same primary NSCLC." (PMID 37754531, 2023). "HHLA2 is significantly related to EGFR mutations and tumor-infiltrating lymphocyte density in LUAD patients." (PMID 36308553, 2023). "The expression of EGFR is closely associated with neo-angiogenesis, tumor invasion and metastasis, whose mutations are a major causative factor for LUAD in East Asian countries (accounting for approximately 60% of LUAD)." (PMID 37065830, 2023). "While EGFR is ubiquitously expressed, EGFR expression is upregulated in several carcinomas and associates with tumor progression and angiogenesis (as reviewed in)." (PMID 37545491, 2023). "Further molecular analysis of tumor tissue by the amplification refractory mutation system (ARMS)—PCR demonstrated an exon 19 deletion of the epidermal growth factor receptor (EGFR) gene." (PMID 38142271, 2023). "In a phase I study involving metastatic NSCLC, amivantamab was screened for varied tumor subgroups, comprising EGFR exon 20 insertions, MET exon 14 and MET amp mutations." (PMID 37970206, 2023). "Tissue or central next-generation sequencing (NGS) circulating tumor DNA (ctDNA) testing was utilized to detect EGFR exon20ins mutations." (PMID 36979929, 2023). "After DMPK assessmentby in vitro microsomal stability and in vivo pharmacokinetics studies, 52 is selected as an orallyactive agent that effectively inhibits tumor formation in animal modelswith T790M-mutated EGFR." (PMID 36749735, 2023). "Bioluminescent images and hematoxylin and eosin (H&E) staining demonstrated that loss of NFAT5 significantly abrogated EGFR-driven tumor growth and enhanced the sensitivity of tumors to TMZ." (PMID 37429858, 2023). "Consistently, lung tumors with EGFR 19del harbored a lower tumor mutation burden than EGFR L858R lung tumors." (PMID 38001917, 2023). "Tumor tissues were assayed using either the cobas EGFR Mutation Test v2 (Roche Diagnostics, Basel, Switzerland), or matrix-assisted laser desorption ionization/time of flight mass spectrometry." (PMID 36915101, 2023). "We fused the fragments to designed ankyrin repeat proteins (DARPins) that target the extracellular domains of HER2 (G3 DARPin28) and EGFR (E01 DARPin29), two well-known tumor-associated antigens." (PMID 36316485, 2023).
tumor (continued). "As can be seen, Endothelial cells are associated with a variety of tumour pathways, including Androgen, EGFR, Estrogen, Hypoxia, JAK-STAT, MAPK, NFKB and TGFb." (PMID 37091857, 2023). "A single tumor tissue sample (8%, 1/13) revealed multiple mutations, including both EGFR exon 19 deletion and p.T790M mutations." (PMID 37372399, 2023). "Among the baseline characteristics of two groups of patients, sex (p = 0.002), EGFR gene mutation status (p < 0.001), and tumour size (p < 0.001) differed before PSM." (PMID 37118722, 2023). "These mutations lead to the constitutive activation of the EGFR signaling pathway, which promotes cell proliferation, survival, and angiogenesis, driving tumor growth and progression." (PMID 37901797, 2023). "HNSCCs express epidermal growth factor receptor (EGFR), which is widely distributed in the tumor surface layer, and increased EGFR expression is often associated with poor prognoses in patients with human epithelial carcinoma." (PMID 38067400, 2023). "A total of 1025 (12.1%, 1025/8485) patients harbored compound EGFR mutations at baseline, that is, two or more distinct EGFR mutations were concomitantly detected in a single tumor sample." (PMID 36829178, 2023). "Because of tumor heterogeneity, patients with different EGFR mutation sites have different sensitivities to targeted drugs." (PMID 37390279, 2023). "EGFR is overexpressed in a variety of tumor cell lines, and high EGFR expression is associated with poor prognosis and low survival rates." (PMID 37629008, 2023). "Among these proteins, AKT and ERK are associated with cell cycle arrest and apoptosis, whereas EGFR influences tumor cell proliferation by interfering with vascular cell metastasis." (PMID 37719860, 2023). "More importantly, the protein ERK5 was identified with the highest correlation with Ki67, indicating the crucial role of ERK5 in promoting tumor cell proliferation in patients with both EGFR amplifications and mutations." (PMID 36720864, 2023). "Our findings indicate that HMJ-38 targets BRD4, CDK2, CHEK1/2, and EGFR, which have been implicated in the death of tumor cells and DNA damage pathways." (PMID 38532833, 2023). "The subsequent NGS testing revealed a novel EGFR p.T751_I759delinsG mutation with 4.68% VAF in the tumor tissue." (PMID 37795433, 2023). "BP maps demonstrated higher specificity, positive predictive value (PPV), and higher diagnostic accuracy, in all tumor lines with the exception of A431 (the highest EGFR-expressing cell line of the group studied)." (PMID 34651290, 2023). "Only around 2% of all compound EGFR mutation-positive patients had more than 2 baseline EGFR mutations, and these patients generally had high tumor mutation loads." (PMID 36829178, 2023). "Overall, the combination of savolitinib and osimertinib has shown promising anti-tumor activity and manageable safety profiles in patients with EGFR mutation, MET amplification, or MET overexpression in NSCLC." (PMID 37835402, 2023). "The MPR and pCR rates increased to 41.2% (7/17; 95% CI 18.4–67.1%) and 23.5% (4/17; 95% CI 6.8–49.9%), respectively, when patients with known tumor EGFR mutations and ALK rearrangements (EGFR/ALK alterations) were excluded in the Nivo+CT arm." (PMID 36928818, 2023). "The most frequently mutated gene was found to be EGFR, with a positive diagnostic rate of 100% in both CSF and tumor tissue, and a rate of 58.33% in patient plasma." (PMID 36937524, 2023). "In summary, we established an effective strategy to screen oncolytic viruses from live-attenuated vaccines and confirmed that the tumor tropism of PRV-LAV was associated with the NRP1/EGFR signaling pathway." (PMID 37891570, 2023). "Another previous study showed that increased VEGF mRNA expression in plasma and tumor stroma was associated with resistance to EGFR-TKIs, and combined EGFR-TKIs and VEGF inhibitors had synergistic antitumor effects in an NSCLC mouse model." (PMID 37854677, 2023).
tumor (continued). "The concordance rate of EGFR mutations between ctDNA and tumour tissue ranges from 66% to 100%, depending on the detection technique used." (PMID 37894366, 2023). "The same applies to the EGFR (epidermal growth factor receptor) inhibitor, which was overexpressed in 27–55% of tumours and was associated with lower patient survival." (PMID 37568604, 2023). "As previously discussed, ambient air PM2.5 appears to stimulate tumor promotion of cells harboring EGFR driver-mutations, such as the L858R mutation." (PMID 37696458, 2023). "Both plasma and tumor tissue were tested using the Cobas assay with a sensitivity of 76.7% (range 70.5–81.9%) for the detection of EGFR-sensitizing mutations and a specificity of 98.2% (range 95.4–99.3%) when using tissue genotypes as reference standards." (PMID 37686506, 2023). "The EGFR gene, located on chromosome 7p11.2, is involved in cell growth, proliferation, and survival, and mutations or overexpression of EGFR have been associated with tumor growth and progression." (PMID 37928523, 2023). "More importantly, patients with both EGFR mutations and amplifications exhibited higher values of the clinical detected tumor proliferative index (evaluated by Ki67 percentage of positive nuclei)." (PMID 36720864, 2023). "For instance, EGFR signaling has been implicated in promoting macrophage infiltration within the tumor, via the chemokine ligand 2 (CCL2)." (PMID 37759950, 2023). "Our findings were consistent with those previous studies, indicating that the GLCM features were correlated to heterogeneity of the tumor, which in turn was associated with the tumor resistance to EGFR-TKIs." (PMID 37730961, 2023). "In a comparison between tumour and plasma EGFR mutation using the cobas EGFR mutation test and ddPCR, the sensitivity of plasma ddPCR was 81%, the specificity was 100%, the positive predictive value was 100%, and the overall concordance was 86%." (PMID 37894366, 2023). "In summary, we proposed the role of 18F-FDG PET/CT and serum tumor markers in recognizing EGFR mutation status in male NSCLC patients." (PMID 37014455, 2023). "Dysregulation of EGFR signaling is associated with numerous diseases, including cancer, where overexpression or mutations in EGFR can lead to uncontrolled cell growth and tumor progression." (PMID 37706181, 2023). "In UTUC, the overexpression of HER2 and EGFR are associated with a high tumor stage, high histological grade, and poor survival." (PMID 37737200, 2023). "First-generation EGFR-TKIs such as gefitinib and erlotinib provide durable tumor shrinkage associated with significant survival benefit in the majority of EGFR-mutated NSCLC patients." (PMID 39516993, 2023). "Somatic mutations of EGFR have been found to be associated with various oncogenic processes, including tumor cell proliferation, angiogenesis, tumor invasion, and metastasis." (PMID 37375228, 2023). "Histopathological findings showed ALK‐negative, EGFR L858R mutation‐positive invasive adenocarcinoma with a programmed death‐ligand 1 tumor proportion score of less than 1%." (PMID 36605695, 2023). "Compared to pyrazole-based inhibitors targeting common tumor-associated targets like EGFR and VEGFR, the development of pyrazole-based BRAF inhibitors has been relatively limited thus far, likely due to challenges such as resistance." (PMID 37628906, 2023). "Our results show that multi-peptide Emut Vax is effective in preventing common EGFR mutation-driven lung tumorigenesis, and the vaccine elicits broad immune responses that are not limited to anti-tumor Th1 response." (PMID 36875137, 2023). "Briefly, mutations in this domain cause abnormal increased autophosphorylation episodes that artificially activate the EGFR and cause the receptor to initiate signaling pathways through signal transducers within the tumor microenvironment." (PMID 37754880, 2023). "Taken together, these results demonstrate CER-1236 anti-tumor function against EGFR mutation-positive NSCLC." (PMID 37194236, 2023).